KDM5B (lysine demethylase 5B)
Diseases named in the same sentence as KDM5B in open-access papers (continued):
Sharing a sentence is not in itself a finding about the gene and the disease.
cervical carcinoma (11 papers, 2010 to 2026). A carcinoma arising from either the exocervical squamous epithelium or the endocervical glandular epithelium. "The structure and function of KDM5C is very similar to the highly tumourogenic KDM5A and KDM5B; it is overexpressed in cervical cancer and increased expression of this gene is associated with disease severity." (PMID 31766427, 2019). "MiR-424-5p inhibited cell proliferation and migration and promoted apoptosis in cervical cancer cell lines by targeting the KDM5B-Notch pathway." (PMID 35409396, 2022). "Moreover, the overexpression of KDM5B in cervical cancer cells reduced apoptosis, and promoted cell migration and invasion by elevating the expression of MMP2/9." (PMID 40940894, 2025). "The overexpression of KDM5B in cervical cancer cells and xenograft tumors led to the accumulation of triglycerides and cholesterol in lipid droplets, by decreasing the expression of carnitine palmitoyltransferase IA and increasing the expression of monoglyceride lipase." (PMID 40940894, 2025). "Similarly, Zhou demonstrated that the expression of miR-424-5p was significantly decreased in cervical cancer tissues and cells, while a dual-luciferase assay confirmed that KDM5B was the direct target gene of miR-424-5p." (PMID 35409396, 2022). "We found CXCL10 expression negatively correlated with KDM5B expression in HPV+ head and neck cancer and positively correlated with STING expression in both HPV+ head and neck cancer and cervical cancer." (PMID 30080846, 2018). "Despite the inability to separate HPV+ and HPV− cervical cancer, we observed significant negative correlation between KDM5B and STING expression in cervical cancer, with a Spearman’s correlation of −0.172." (PMID 30080846, 2018).
Intellectual disability (11 papers, 2017 to 2026). "Loss-of-function mutations in the histone demethylases KDM5A, KDM5B or KDM5C are found in patients with intellectual disability and ASD." (PMID 41648108, 2026). "In individuals with an intellectual disability or developmental delay, KDM5B mutations often follow a recessive inheritance pattern with homozygous or compound heterozygous mutations." (PMID 38997333, 2024). "Genetic variants in KDM5B have been previously associated with moderate to severe developmental delay/intellectual disability (DD/ID), autism spectrum disorders (ASD), and dysmorphism." (PMID 34573379, 2021). "Gene ontology analysis by IPA software revealed that transcriptional targets of AR, KDM5B, and SMAD4 that were differentially expressed in response to BPA treatment were significantly associated with “autism spectrum disorder or intellectual disability”." (PMID 36803626, 2023). "In contrast to the gain of function seen in cancer cells, loss of function variants in the autosomal paralogs KDM5A, KDM5B, and the X-linked KDM5C have been observed in individuals with intellectual disability." (PMID 36803422, 2023). "Whole-exome sequencing of individuals with intellectual disability has identified loss of function mutations in KDM5A, KDM5B and KDM5C." (PMID 31862793, 2019). "In contrast to intellectual disability, which is exclusively associated with loss-of-function mutations in KDM5 genes, malignancies have been associated with overexpression of KDM5A or KDM5B, either loss or gain of KDM5C, or loss of KDM5D." (PMID 31862793, 2019). "Examples include SUMF1, KDM5B and MXRA5 (Known-ASD genes), PRODH2 and KCTD21 (implicated in schizophrenia), as well as USP9X and SMS (implicated in intellectual disability)." (PMID 28720891, 2017). "Changes to protein interactions could also contribute to the intellectual disability seen in individuals with genetic variants in KDM5A, KDM5B, or KDM5C." (PMID 36803422, 2023). "Examples include PRODH2 and KCTD21 (implicated in schizophrenia), USP9X and SMS (implicated in intellectual disability), TRIM9 and KDM5B (known-ASD genes), and others such as AGL and MOGS (candidate genes involved in energy metabolism and immune responses, respectively)." (PMID 28720891, 2017). "However, individuals with ADHD in our study harboring ultra-rare de novo PTV variants in KDM5B did not have diagnoses of ASD or intellectual disability." (PMID 38997333, 2024). "In addition to AR targets, KDM5B targets dysregulated in male and female pups, and SMAD4 targets dysregulated in male pups were also significantly associated with “autism spectrum disorder or intellectual disability”." (PMID 36803626, 2023). "Moreover, two genes in the KDM5 family, KDM5B and KDM5C, are disrupted in neurodevelopmental disorders, including intellectual disability and ASD." (PMID 33350388, 2020). "The absence of intellectual disability is also observed in other genes (for example, SCAF1, HNRNPUL2, GIGYF1, KDM5B and KMT2C) with substantial contribution from rare inherited variants and modest effect size." (PMID 35982159, 2022).
bladder cancer (8 papers, 2010 to 2023). "Knockdown and apoptosis studies demonstrated the close link of KDM5B, in cell cycle regulation and cancer cell maintenance, in bladder cancer cell lines." (PMID 32751840, 2020). "A potential inverse connection between KDM5B and connexin 26 (CX26) in the progression of bladder cancer was reported, where KDM5B was found to be upregulated in contrast to CX26." (PMID 32751840, 2020). "We also found that E2F transcription factor 1 (E2F1) and E2F transcription factor 2 (E2F2) are candidate downstream modulators regulated by KDM5B in bladder cancer and NSCLC." (PMID 30344945, 2018). "Transfection of KDM5B-specific siRNA into various bladder cancer cell lines significantly suppresses the proliferation of cancer cells and increased the number of cells in sub-G1 phase." (PMID 23579952, 2013). "From the results, Cx26 and KDM5B can be a novel combined adjuvant biomarker for bladder cancer diagnosis." (PMID 23579952, 2013). "Taken together, these results indicate that KDM5B represses Cx26 expression in the bladder cancer development." (PMID 23579952, 2013). "We then analyzed the expression patterns of KDM5B in a number of clinical samples derived from Japanese bladder cancer subjects examined by cDNA microarray, and confirmed its significant overexpression (P < 0.0001, Mann-Whitney's U-test)." (PMID 20226085, 2010). "Cx26 is down-regulated by KDM5B in the progression of bladder cancer." (PMID 23579952, 2013). "From the inverse expression pattern of Cx26 and KDM5B in bladder neoplasm, Cx26 expression may be down-regulated by KDM5B in the progression of bladder cancer." (PMID 23579952, 2013). "Therefore, we analyzed 123 bladder cancer samples and 23 normal control samples (British) and confirmed significant elevation of KDM5B expression in tumor cells compared with in normal cells (P < 0.0001, Mann-Whitney's U-test)." (PMID 20226085, 2010). "Several other cancers that showed genomic amplifications of KDM5B gene, e.g., thymic tumors (THYM), cholangiocarcinoma (CHOL), esophageal cancers (ESCA), GBM and bladder cancer (BLCA), also exhibited increased or trend of increased KDM5B expression." (PMID 33245716, 2020). "Overexpression of KDM5B was noted in the early and advanced stages of bladder cancer, irrespective of cancer grade." (PMID 32751840, 2020). "Connexin 26 (Cx26) expression is down-regulated and KDM5B (H3K4 demethylase) is up-regulated in the progression of bladder cancer, suggesting that Cx26 expression may be down-regulated by KDM5B in bladder cancer." (PMID 23579952, 2013). "Quantitative RT-PCR analysis confirms that expression levels of KDM5B are significantly higher in human bladder cancer tissues than in their corresponding non-neoplastic bladder tissues (p < 0.0001)." (PMID 23579952, 2013). "Quantitative RT-PCR analysis confirmed that expression levels of KDM5B are significantly higher in human bladder cancer tissues than in their corresponding non-neoplastic bladder tissues (P < 0.0001)." (PMID 20226085, 2010).
leukemia (8 papers, 2017 to 2022). A malignant (clonal) hematologic disorder, involving hematopoietic stem cells and characterized by the presence of primitive or atypical myeloid or lymphoid cells in the bone marrow and the blood. "KDM5B inhibits initiation of leukaemogenesis in leukaemias expressing MLL fusion proteins by reducing the high levels of H3K4me3 required by the leukaemic stem cells (LSCs) for proliferation." (PMID 35406676, 2022). "For example, Ikaros-mediated repression of KDM5B depends on binding histone deacetylase (HDAC) to the upstream regulatory elements of KDM5B, regulating the epigenetic signature in leukemia." (PMID 34096883, 2021). "Importantly, KDM5B is an H3K4 demethylase that is induced in differentiated leukemia cells, and the overexpression of KDM5B abrogates the oncogenic potential of LSC in MLL-rearranged AML." (PMID 35805040, 2022). "The authors argue that KDM5B may regulate the expression of several oncogenes and tumor suppressors, witnessed in both solid tumors, as well as in leukemia." (PMID 34944554, 2021). "We identified the chromatin state of the Ikaros gene targets in ALL leukemia cells and found that Ikaros suppresses the expression of its targets by recruiting H3K9me3 or H3K27me3, and up-regulates gene expression by increasing the binding of H3K4me3 via KDM5B in the promoter region of its targets." (PMID 28030830, 2017). "On the other hand, KDM5B suppressed leukemogenesis and induced Acute Myeloid Leukemia (AML) cells to differentiate out of the leukemia stem cell compartment." (PMID 31776402, 2019). "Suppression of KDM5B significantly promoted disease progression, whereas its overexpression inhibited MLL leukaemia." (PMID 27593928, 2017). "KDM5B shows reduced expression in the more differentiated leukaemic cells, so targeting KDM5B or other KDM5 proteins in leukaemia may not be an option." (PMID 35406676, 2022).
developmental delay (7 papers, 2016 to 2024). "There is evidence that KDM5B haploinsufficiency may be associated with a phenotype of developmental delay, although its penetrance is incomplete." (PMID 34573379, 2021). "De novo mutations of Kdm5b result in a recognizable syndrome with developmental delay." (PMID 33362469, 2020). "For example, recessive histone lysine methylation defects caused by homozygous or compound heterozygous variants in KDM5B (lysine demethylase 5B, MIM# 605393) result in a recognizable neuropsychiatric syndrome characterized by developmental delay, ID, facial dysmorphism, and camptodactyly." (PMID 39519104, 2024). "In the Olson study, KDM5B, NAV1, and KIF21B were identified as candidate genes for developmental delay from two patients with microduplications of 1q32.1, and these genes are all common to the deleted region of our patient." (PMID 26955491, 2016).
oral carcinoma (7 papers, 2018 to 2024). "KDM5B is required for stem cell function in oral cancer, and KDM5B-high cells are a definite sub-population in oral carcinoma that exhibits typical cancer stem cell (CSC)-related markers and PI3K signaling activation." (PMID 37887281, 2023). "In this regard, LSD1 knockdown sensitized cells to 5-fluorouracil, while the inhibition of KDM5B improved radiosensitivity in oral cancer cells." (PMID 35326475, 2022). "In addition, silencing of KDM5B blocked oncogenicity, stemness and augmented radiation sensitivity in human oral carcinoma." (PMID 35333349, 2022). "The use of the inhibitor of KDM5B CPI-455 depleted the fraction of CD44+ and ALDH+ oral cancer stem cells and attenuated tumorsphere formation, while it did not affect cell viability or apoptosis." (PMID 35326475, 2022). "It was hypothesized that KDM5B is responsible for the formation of tumor-initiating cells by promoting the reprogramming and de-differentiation of non-malignant oral cancer cells into stem-like cells." (PMID 35326475, 2022).
neuroblastoma (6 papers, 2015 to 2024). Neuroblastoma (NB) is the most common solid, extracranial childhood tumor. "Another study reported that KDM5B knockdown reduced neuroblastoma tumor sphere size and significantly enhanced DDP sensitivity." (PMID 39039611, 2024). "Overexpression of KDM5B can enhance the tumorigenicity and drug resistance of neuroblastoma in the nervous system diseases." (PMID 30728054, 2019). "The expression of KDM5B can enhance the tumorigenicity and drug resistance of neuroblastoma." (PMID 30728054, 2019). "Moreover, KDM5B expression played a critical role in chemo-resistance and stem cell-like phenotype of neuroblastoma cells as KDM5B-silenced cells gained a decreased tendency for tumor sphere formation and invasion, but became more susceptible towards cisplatin treatment." (PMID 27974677, 2017).
prostate tumors (6 papers, 2015 to 2025). "In partial support of this connection, KDM5B mRNA levels were significantly reduced in post-ADT (castration-resistant) patient prostate tumors." (PMID 33245716, 2020). "Next we analyzed the KDM5B mRNA levels in TCGA PRAD dataset comparing normal and prostate tumor tissues." (PMID 33245716, 2020). "Further studies revealed that SKP2 inactivation contributes to the elevation of Jumonji/ARID1 B (JARID1B) (also named as KDM5B or PLU1) protein through TRAF6-mediated ubiquitination in cultured PCa cells and prostate tumors of mice." (PMID 25734985, 2015). "Moreover, KDM5B is overexpressed in prostate tumor tissues, especially in mice that do not express PTEN and exhibit hyperactivation of the AKT pathway due to the absence of PTEN." (PMID 38004468, 2023).
Cognitive impairment (5 papers, 2021 to 2025). Abnormal cognition is characterized by deficits in thinking, reasoning, or remembering. "To date, approximately a dozen cases with pathogenic KDM5B variants have been reported, all of whom had cognitive impairment ranging from mild to severe." (PMID 34573379, 2021). "Our findings show that KDM5B functions in the adult hippocampus to control learning and memory and imply that at least some of the cognitive deficits associated with KDM5B deficiency could be amenable to treatment in adults." (PMID 38575342, 2024). "A particularly intriguing example for how diseases with cognitive impairment and adult cognitive function intersect is KDM5B, a gene that encodes a histone lysine demethylase with roles in neuronal differentiation, which we interrogated further in humans and mice." (PMID 37231097, 2023). "Our analyses support that PTVs and missense variants in KDM5B, GIGYF1 and CACNA1A underlie a continuum of conditions with various degrees of cognitive impairment." (PMID 37231097, 2023).
colorectal cancer (5 papers, 2015 to 2026). A primary or metastatic malignant neoplasm that affects the colon or rectum. "KDM5B upregulation was significantly negatively correlated with the survival rates in various cancer types, including thyroid, lung, esophageal and colorectal cancers." (PMID 41654562, 2026).
esophageal squamous cell carcinoma (5 papers, 2013 to 2025). Esophageal squamous cell carcinoma (ESCC) is a type of esophageal carcinoma (EC) that can affect any part of the esophagus, but is usually located in the upper or middle third. "P. gingivalis promotes esophageal squamous cell carcinoma progression by mediating immune checkpoints B7-H4 and KDM5B." (PMID 40843171, 2025).
ovarian carcinoma (5 papers, 2013 to 2020). A malignant neoplasm originating from the surface ovarian epithelium. "Recent data has shown that KDM5B exhibits frequent gain of function for alterations in ovarian cancer and the high level of KDM5B is closely associated with poor outcome and acquired drug resistance in malignant ovarian tumor." (PMID 30064416, 2018). "KDM5B may act as a key biomarker to predict prognosis and acquired chemoresistance for patients with ovarian carcinoma." (PMID 30064416, 2018). "JARID1B/KDM5B, which selectively demethylates H3K4me3, serves as a good prognosis predictor in NSCLC, breast and ovarian cancer." (PMID 30591630, 2018).
pancreatic cancer (5 papers, 2022 to 2025). "Another study also pointed to the association between KDM5B and Wnt/β-catenin signaling in pancreatic cancer." (PMID 40940894, 2025). "Together, these data suggest that KDM5B is overexpressed in GEM-treated PDX pancreatic cancer with SMAD4 loss." (PMID 38789418, 2024). "KDM4B and KDM5B were associated with DSB recognition and homologous recombination (HR) pathway in breast and pancreatic cancer, respectively." (PMID 40940894, 2025). "KDM5B encourages epithelial-mesenchymal transition in cancer cells and stimulates the progression of pancreatic cancer." (PMID 38842683, 2024). "Furthermore, KDM5B depletion regulated innate immunity by increasing STING expression, which was associated with increased expression of IFNγ, and enhanced T cell infiltration in a pancreatic cancer in vivo model." (PMID 40940894, 2025). "We employed multiple public databases to reveal that the expression of KDM5A, KDM5B, and KDM5C (all members of the KDM5 family) is significantly increased in pancreatic cancer." (PMID 35493099, 2022).
triple-negative breast carcinoma (5 papers, 2016 to 2023). An invasive breast carcinoma which is negative for expression of estrogen receptor (ER), progesterone receptor (PR), and human epidermal growth factor receptor 2 (HER2). "Our immunoprecipitation experiments supported serine phosphorylation of KDM5B in a triple negative breast cancer cell line, MDA-MB-231." (PMID 31776402, 2019). "Interestingly, in triple-negative breast cancers, there are differing opinions regarding the role of KDM5B." (PMID 38004468, 2023). "We posit that systemic hsa-miR-448 inoculation, targeting the expression and/or activities of KDM5B may be a stride in the right direction in combating the menace of triple negative breast cancer." (PMID 26917489, 2016). "Furthermore, we showed that the microRNA, hsa-miR-448 significantly inhibits MALAT-mediated oncogenic and metastatic potential by directly suppressing the expression of KDM5B in triple negative breast cancer, thus, alluding to the clinicopathophysiologic relevance of these findings." (PMID 26917489, 2016). "In triple-negative breast cancer (TNBC) cells, the lysine-specific demethylase 5B (KDM5B) promoted MALAT1 expression, which in turn enhanced the invasion and clonogenic potential in in vitro and in vivo models." (PMID 29739426, 2018). "In this study, we demonstrated the critical roles of KDM5B and its downstream target MALAT1 in triple negative breast cancer metastatic phenotype and clinical prognosis, based on the following observations: (i)." (PMID 26917489, 2016). "Moreover, KDM5B inhibited the expression of pluripotency genes, SOX2 and NANOG, and decreased the stem cell population in triple-negative breast cancer cell lines (TNBC)." (PMID 31776402, 2019). "In addition, the ectopic expression of KDM5B and its downstream effector gene, MALAT1, inversely corrected with that of hsa-miR-448 in the triple negative breast cancer cells." (PMID 26917489, 2016).
autism (4 papers, 2016 to 2026). Persistent deficits in social interaction and communication and interaction as well as a markedly restricted repertoire of activity and interest as well as repetitive patterns of behavior. "The LoF variants in this gene and several members of the same family (KDM3A, KDM5B, KDM6B) have recently been associated with autism in a large scale genetic investigation." (PMID 27257017, 2016). "Additionally, 4 novel genes, POGZ, KDM5B, NAA15, and FRYL, harbored at least two de novo mutations in both CHD and autism cohorts." (PMID 34735430, 2021).